MYCN (MYCN proto-oncogene, bHLH transcription factor)
Diseases named in the same sentence as MYCN in open-access papers (continued):
Sharing a sentence is not in itself a finding about the gene and the disease.
neuroblastoma (continued). "SMARC genes were identified as inferred transcriptional regulators of MYCN-bound genes (ChIP-seq), their expression showed strong correlation to neuroblastoma outcome, and SMARCA inhibition strongly reduced IMR32 cell viability." (PMID 33968920, 2021). "Amplification of the MYCN oncogene and consequent overexpression of the MYCN oncoprotein occur in 25% of neuroblastoma patients and correlate with poor patient survival." (PMID 33767157, 2021). "Similar results were found in rodent in vivo models of CLL, T-cell acute lymphoblastic leukaemia (T-ALL), GBM, cholangiocarcinoma using THZ1 and leukaemia model and MYCN-amplified neuroblastoma using CYC065." (PMID 34344865, 2021). "have reported co-amplification of the lncUSMycN with MYCN in a portion of human neuroblastoma samples." (PMID 33718173, 2021). "Early in vitro models demonstrated elevated MYCN expression induced neuroblastoma tumour growth and proliferation, while transgenic mouse and zebrafish models with induced MYCN expression underwent spontaneous neuroblastoma formation." (PMID 34064704, 2021). "Our studies imply that elevated MYCN expression in MNA neuroblastoma involve mechanisms uncoupling MYCN-driven expression of miR-17-92 miRNAs from the inhibition of MYCN mRNA by feed-back regulation." (PMID 34026620, 2021). "By comparing the IC50 values of Torin-1, Torin-2, AZD3147 and PP242 we established that only Torin-2 inhibited cell viability of all three MycN-amplified neuroblastoma cell lines tested at nanomolar concentration." (PMID 33390782, 2021). "Following this principle, inhibition of N-MYC in MYCN-amplified neuroblastoma cell lines induced a differentiation morphology as well as upregulation of neural differentiation genes." (PMID 33718380, 2021). "This SAHA + SE486-11 combination therapy screen revealed that MYCN-amplified neuroblastoma cell lines were the most sensitive cell lines." (PMID 33658627, 2021). "Two oncogenes, MYCN and mutationally activated ALK (the most commonly mutated genes in primary neuroblastoma and an attractive candidate for targeted therapy), were expressed under control of the dopamine-beta-hydroxylase (dβh) promoter." (PMID 33800887, 2021). "Despite multimodal therapy including chemotherapy, surgery, radiotherapy, myeloablative therapy with autologous transplant, and immunotherapy, survival rates for MYCN‐amplified neuroblastoma patients remain poor." (PMID 33497018, 2021). "Silencing endogenous USP3 with USP3 siRNA-1 or USP3 siRNA-2 (lanes 2–3 and 5–6) in MYCN-amplified neuroblastoma cells significantly decreased MYCN protein expression." (PMID 33767157, 2021). "Rapamycin/sirolimus is a well-known mTOR inhibitor with reported therapeutic efficacy on aggressive MYCN amplified neuroblastomas." (PMID 34199959, 2021). "The RTNs reported here showed significant MYCN silencing in vitro in neuroblastoma cells with little cytotoxicity." (PMID 35712226, 2021). "This highlights new avenues to pursue the targeting of post-transcriptional regulation in cancer, in particular the strongly 3’UTR-dependent regulation of MYCN mRNA in MNA neuroblastoma." (PMID 34026620, 2021). "It has been shown in MYCN-amplified neuroblastoma that the protein synthesis machinery is significantly upregulated." (PMID 33804256, 2021). "The use of MRE11 exonuclease inhibitor mirin increased the RS and DNA damage biomarkers in MYCN-amplified neuroblastoma cells until death in vitro and induced apoptosis in vivo." (PMID 34201502, 2021).
neuroblastoma (continued). "The driver role of MYCN in neuroblastoma initiation has been supported through murine and zebrafish models overexpressing MYCN in the developing sympathetic neuronal lineage." (PMID 34638267, 2021). "Functional support for the applicability of epigenetic targeting compounds was provided by the fact that 43 of the 45 epigenetic library compounds reduced the viability of MYCN amplified neuroblastoma cells." (PMID 33968920, 2021). "We found that DDX21 promotes MYCN‐amplified neuroblastoma cell proliferation and clonogenic capacity, and high DDX21 gene expression correlates with poor patient prognosis." (PMID 33497018, 2021). "Loss of 11q is largely mutually exclusive with amplification of the MYCN oncogene, the most well-established oncogenic driver in neuroblastoma." (PMID 34230973, 2021). "In mouse models of MYCN‐amplified neuroblastoma, DDX21 knockdown initially induces tumor regression, suppresses tumor progression, and significantly improves the overall survival." (PMID 33497018, 2021). "In contrast, the repression of the prognostic neuroblastoma marker, MYCN, resulted in less aggressive cell behaviour." (PMID 33578855, 2021). "AT7519, a CDK2 inhibitor (70.0% cytotoxicity), has shown excellent preclinical anti-tumor responses against MYCN-amplified neuroblastoma, and is currently in phase II clinical trials for adults (NCT00390117) and children (NCT01627054)." (PMID 34722256, 2021). "We further investigated the phenotypic effect of USP3 knockdown in MYCN-amplified neuroblastoma cell lines with high USP3 expression." (PMID 33767157, 2021). "Neuroblastoma that presents with MYCN amplification is highly malignant and treatment evasive, increasing the rate of tumor recurrence and mortality in children afflicted with this devastating disease." (PMID 34422720, 2021). "EVs produced by MYCN-expressing cells or isolated from neuroblastoma patients induced the Warburg effect, proliferation and c-MYC expression in target cells." (PMID 34847775, 2021). "For example, BMI1, a core component of the PRC1 complex, has been shown to cooperate in MYCN-driven neuroblastomas by inhibiting cell death and differentiation." (PMID 34638328, 2021). "We saw significant positive correlations between USP3 and MYCN expression levels in neuroblastoma tissues." (PMID 33767157, 2021). "All six of the SMARC genes, identified as being ITRs of MYCN’s genomic targets (ChIP-seq), were able to segregate neuroblastoma patients by outcome, according to the level of SMARC gene expression in tumours." (PMID 33968920, 2021). "MRE11 is essential to prevent deleterious accumulation of DNA damage and its increased expression in MYCN-amplified neuroblastoma is required to restrain MYCN-dependent RS." (PMID 34201047, 2021). "Two ctDNA-plasma positive samples from MYCN-neuroblastoma patients were used for the assay validation, with tissue samples for each patient used as a positive control and run in duplicate." (PMID 34169282, 2021). "We aimed to develop and validate the CT-based machine learning models for predicting MYCN amplification in pediatric abdominal neuroblastoma." (PMID 34109133, 2021). "CDK1 inhibition resulted in elevation of miR-34a, meanwhile miR-34a suppression up-regulated the expression of MYCN and enhanced cell survival of neuroblastoma cells treated with CDK1 antagonist." (PMID 33773546, 2021). "MYB regulates the neuroblastoma oncogene MYCN, by controlling its expression and amplification in neuroblastoma lines." (PMID 33466745, 2021). "Neuroblastoma COG (Children's Oncology Group) risk stratification is mainly based on MYCN gene amplification, age, INSS (International Neuroblastoma Staging System) staging and other factors." (PMID 34838090, 2021).
neuroblastoma (continued). "Other proteins linked to metabolism such as eEF2, PFKP, GAPDH and ribosomal protein L10a were also confirmed to be enriched in the EVs secreted by MYCN-positive neuroblastoma cells." (PMID 34847775, 2021). "According to a previous report, MYCN expression determines anti-cancer drug sensitivity in neuroblastoma cells." (PMID 34591871, 2021). "Our findings provide strong evidence that enforced expression of MYCN in MNA neuroblastoma essentially relies on IGF2BP1." (PMID 34026620, 2021). "DpC suppressed MYCN expression and total protein levels, which proves its multimodal effect on one of the most prominent prognostic factors in neuroblastoma." (PMID 35008802, 2021). "In mice, the ectopic expression of neuroblastoma oncogenes, MYCN and (anaplastic lymphoma kinase) ALK, in neural crest precursors was sufficient to drive tumorigenesis in a transplant model." (PMID 34771457, 2021). "Our findings support a potential role for MYCN amplification in treatment resistance of neuroblastoma cells that merits further investigation." (PMID 34011385, 2021). "We conclude that the observed ALYREF binding is biologically significant in the context of malignant cells, however, the exact role of ALYREF in regulating MYCN-dependent or -independent gene transcription in neuroblastoma remains largely undetermined." (PMID 33767157, 2021). "In MYC-driven medulloblastoma models, OTX015 IC50 between 142.6 nM and 448.6 nM have been reported, while in MYCN-driven neuroblastoma, IC50s span from 37 nmol/L to >1 μmol/L." (PMID 33668642, 2021). "In neuroblastoma, MYCN amplification is found in approximately 20% of cases and is associated with high-risk disease and poor prognosis." (PMID 34552068, 2021). "CAI2 expression has been higher in advanced-stage neuroblastomas in an independent manner from MYCN amplification." (PMID 33718173, 2021). "To corroborate these findings, we re-analyzed the expression of miRNAs predicted to target MYCN mRNA in neuroblastoma." (PMID 34026620, 2021). "This is because the PKM2 isoform is enriched in MYCN-amplified neuroblastoma cells due to the ability of the MYC transcription factors to transactivate the splicing factors PTBP1 and HNRNPA." (PMID 34847775, 2021). "We showed that this variant impacts the ability of MYCN to regulate ODC1, and that it also influences outcome in neuroblastoma, with the rarer variant associated with a better survival." (PMID 33918978, 2021). "Regarding morphologic features of INPC, the MKI, which has been implicated as highly proliferative, and the undifferentiated tumor subtype are hallmarks of the unfavorable histology and are frequently detected in MYCN-amplified neuroblastomas." (PMID 34069817, 2021). "Given the well-established link between the MYCN oncogene and neuroblastoma patient outcome, the response of neuroblastoma cell lines with varying MYCN status to CBP/p300 inhibition was assessed." (PMID 33968920, 2021). "Pairwise comparisons showed that, as expected, MYCN was significantly overexpressed in neuroblastoma datasets compared with the adult tumor datasets, whereas the inverse was seen for MYC." (PMID 33918978, 2021). "In neuroblastoma, TCF3 shows increased expression in MYCN amplified tumors, and its increased expression is linked to poor prognosis." (PMID 33466745, 2021). "This is exacerbated in combination with other gene alterations, such as MYCN amplifications, which then can lead to neuroblastoma formation." (PMID 34769149, 2021). "Previous studies have shown that down-regulation of MYCN is a critical early event that is necessary to facilitate neuroblastoma cell differentiation in cells treated with ATRA." (PMID 34669465, 2021). "Using microRNA trapping by RNA affinity purification, we provide a comprehensive view of MYCN-regulatory miRNAs in neuroblastoma-derived cells, confirming a pivotal role of the miR-17-92 cluster and moderate association by the let-7 miRNA family." (PMID 34026620, 2021).
neuroblastoma (continued). "Our work investigated in details the relationship of MYCN with the immune system, finding a correlated immune-suppressive phenotype in neuroblastoma (NB) and different cancers where MYCN is up-regulated." (PMID 33718189, 2021). "In neuroblastoma patients for instance, gene set enrichment analysis has shown that MYCN levels negatively correlate with genes involved in different immune system pathways, especially those associated to interferon gamma and phagocytosis." (PMID 34195095, 2021). "MYCN is amplified or overexpressed in one third of children with neuroblastoma, and, is a driver in several other human cancer types." (PMID 33658627, 2021). "As observed in cell lines, the most frequently mutated single gene except for MYCN was ALK, with SNVs in 5 neuroblastomas and a gain in 1 neuroblastoma." (PMID 34442335, 2021). "Here, we addressed this question by using multiple in vitro and in vivo preclinical models of MYCN-driven neuroblastoma and medulloblastoma." (PMID 34508175, 2021). "Expression of the oncofetal IGF2BP1 is upregulated in MNA neuroblastoma, promotes MYCN protein and RNA expression, and is considered a potent and conserved inhibitor of miRNA-dependent downregulation of oncogenic factors in cancer." (PMID 34026620, 2021). "We have identified a unique and novel mechanism of therapeutic efficacy using these small molecule imipridones in malignant MYCN-amplified neuroblastoma cells." (PMID 34422720, 2021). "For example, in MYCN-amplified neuroblastoma, the TFs MYCN, HAND2, ISL1, PHOX2B, GATA3, and TBX2 are essential for maintaining cell state and survival." (PMID 34712617, 2021). "In a syngeneic mouse model of neuroblastoma (TH-MYCN), c-MYC expression is detected in stromal cells surrounding nests of MYCN-positive neuroblastomas." (PMID 34847775, 2021). "Here our analyses identify ALYREF, expressed from the most common genetic copy number variation in neuroblastoma, chromosome 17q21-ter gain as a key regulator of MYCN protein turnover." (PMID 33767157, 2021). "Neuroblastoma cell identity depends on a core regulatory circuit (CRC) of transcription factors that collaborate with MYCN to drive the oncogenic gene expression program." (PMID 34669465, 2021). "In line, we detected 29 MYCN-amplified neuroblastomas, but also 42 TERT rearrangements and 8 ATRX alterations." (PMID 34442335, 2021). "Importantly, it has been known since the 1980s that MYCN amplification is directly associated with low major histocompatibility complex expression, and it has been confirmed more recently that MYCN‐amplified neuroblastomas have one of the most immune cell excluded TMEs of all human cancer." (PMID 33314654, 2021). "All six MYCN target genes (ChIP-seq) which were common to at least two of the three lists, had prognostic value for neuroblastoma patient outcome, when patients were segregated according to expression of these genes." (PMID 33968920, 2021). "First, we show that in neuroblastoma cells MYCN and USP5 together stimulate a forward feedback expression loop maintaining high expression of each protein." (PMID 33658627, 2021). "In neuroblastoma, frequent MYCN amplification and chromosome 17q gain are found only in advanced stages of the disease, so they are unlikely to be the initiating rate-limiting events." (PMID 34434669, 2021). "The Aurora Kinase A inhibitor MLN8237 that also induces mitotic arrest, enhances Venetoclax activity in MYCN-amplified neuroblastoma and of Navitoclax in pancreatic adenocarcinoma." (PMID 34581776, 2021). "In fact, pharmacological inhibition of MRE11 by mirin inhibited tumor growth of MYCN-amplified neuroblastoma xenografts." (PMID 34069817, 2021). "Our data demonstrate that DDX21 and CEP55 are potential therapeutic targets for MYCN‐amplified neuroblastoma." (PMID 33497018, 2021). "Stable inhibition of ALYREF by ALYREF shRNA (lanes 6–10) in cycloheximide-treated, MYCN-amplified neuroblastoma cells reduced MYCN protein half-life from 36–40 to 14–15 min." (PMID 33767157, 2021).